N4BP1 (NEDD4 binding protein 1)
Description:
Potent suppressor of cytokine production that acts as a regulator of innate immune signaling and inflammation. Acts as a key negative regulator of select cytokine and chemokine responses elicited by TRIF-independent Toll-like receptors (TLRs), thereby limiting inflammatory cytokine responses to minor insults. In response to more threatening pathogens, cleaved by CASP8 downstream of TLR3 or TLR4, leading to its inactivation, thereby allowing production of inflammatory cytokines (By similarity). Acts as a restriction factor against some viruses, such as HIV-1: restricts HIV-1 replication by binding to HIV-1 mRNAs and mediating their degradation via its ribonuclease activity. Also acts as an inhibitor of the E3 ubiquitin-protein ligase ITCH: acts by interacting with the second WW domain of ITCH, leading to compete with ITCH's substrates and impairing ubiquitination of substrates (By similarity).
Tractability: PROTAC: UniProt records ubiquitination sites on it; ubiquitination databases record sites on it; its protein half-life has been measured.
Gene: Protein-coding gene on chromosome 16 (48,538,726 to 48,620,148, reverse strand). Ensembl gene ENSG00000102921.
Subcellular location: Cytoplasm, cytosol; Nucleus; Nucleus, nucleolus; Nucleus, PML body
Subcellular location (Human Protein Atlas): Nucleoli fibrillar center; Cytosol; Nucleoplasm
Pathways (Reactome):
Immune System: Regulation of NF-kappa B signaling
Gene Ontology:
Molecular function: mRNA binding; protein binding; RNA nuclease activity; ubiquitin binding
Biological process: cellular response to UV; negative regulation of viral genome replication; negative regulation of cytokine production; negative regulation of proteasomal ubiquitin-dependent protein catabolic process; negative regulation of protein ubiquitination; regulation of innate immune response
Cellular component: cytosol; nucleolus; nucleus; PML body
Genetic constraint (gnomAD): Loss-of-function variants: 18 observed, 57.62 expected, observed/expected ratio (o/e) 0.31, 90% interval 0.22 to 0.46. The upper end of that interval is the gene's LOEUF score, 0.46, which puts it in group 2 of 6, group 1 being the genes least tolerant of losing a copy. Missense variants: 896 observed, 993.85 expected, observed/expected ratio (o/e) 0.9, 90% interval 0.85 to 0.95. Synonymous variants: 370 observed, 366.47 expected, observed/expected ratio (o/e) 1.01, 90% interval 0.93 to 1.1.
Homologues: Orthologues: chimpanzee N4BP1 (99% identical), macaque N4BP1 (98% identical), dog N4BP1 (90% identical), pig N4BP1 (90% identical), rabbit N4BP1 (86% identical), rat N4bp1 (81% identical), mouse N4bp1 (81% identical), guinea pig N4BP1 (80% identical), tropical clawed frog n4bp1 (45% identical), zebrafish n4bp1 (37% identical), Drosophila melanogaster Regnase-1 (14% identical), Caenorhabditis elegans rege-1 (13% identical), and 4 more. Paralogues in human: KHNYN (24% identical), NYNRIN (23% identical), ZC3H12C (15% identical), ZC3H12A (15% identical), ZC3H12B (14% identical), ZC3H12D (12% identical).